PLOD2 (procollagen-lysine,2-oxoglutarate 5-dioxygenase 2)
Diseases named in the same sentence as PLOD2 in open-access papers (continued):
Sharing a sentence is not in itself a finding about the gene and the disease.
tumor (continued). "UBE2C, CCNB1, CCNB2, PLOD2, NUP210, MELK, CDC20 were overexpressed in tumours and in CIN3/CIS relative to both Normal and CIN1/CIN2, suggesting that they could have an important role to play in the early phase of tumorigenesis." (PMID 21338529, 2011). "UBE2C, CCNB1, CCNB2, PLOD2, NUP210, MELK, CDC20 genes were overexpressed in tumours and in CIN3/CIS relative to both Normal and CIN1/CIN2, suggesting that they could have a role to play in the early phase of tumorigenesis." (PMID 21338529, 2011). "Additionally, genes like COL4A1, PLOD2, and PXDN, which participate in extracellular matrix remodeling, alongside immune-related genes such as CYFIP2, EMP3, and HLA-B, are instrumental in modulating the tumor microenvironment and facilitating immune evasion." (PMID 39949776, 2025). "Specifically, KLF6, BCL2, ETS1, and PLOD2 could provide insights into tumor biology, hypoxia adaptations, and aggressiveness without invasive biopsies." (PMID 40500522, 2025). "Additionally, the collagen-modifying enzyme procollagen-lysine,2-oxoglutarate 5-dioxygenase 2 (PLOD2), which is overexpressed in many tumors relative to normal tissues, has been shown to promote immune evasion in UPS, contributing to tumor metastasis and CD8+ T cell dysfunction." (PMID 41300979, 2025). "Furthermore, TGFBI, PLOD2 and APOL1 had clear tumor progression patterns in the TCGA-KIRC dataset." (PMID 38680858, 2024). "Our analysis of human CRC tissue sections revealed that PLOD2 was exclusively expressed in the stem cell compartment (at the bottom of the colonic crypts) of the normal mucosa, while its expression was increased at the invasive edge of the CRC tissue and also throughout the tumor tissue." (PMID 33805564, 2021). "In detail, tumor-derived plasminogen activator inhibitor 1 (PAI-1), through the induction of the PI3K/AKT pathway in CAAs, activates the expression of procollagen-lysine 2-oxoglutarate 5-dioxygenase 2 (PLOD2) that induces the alignment of collagen I fibers, further promoting BC metastasis." (PMID 33917351, 2021). "PLOD2 (2‐oxoglutarate 5‐dioxygenase 2), an intracellular enzyme belonging to the PLOD family, plays a critical role in collagen modification, cell migration, and pulmonary metastasis with no impact on primary tumor growth." (PMID 35789544, 2023).
cancer (92 papers, 2008 to 2025). A tumor composed of atypical neoplastic, often pleomorphic cells that invade other tissues. "Further analysis revealed that proteins carried by the nanoparticles included various neoantigens derived from mutations recorded in the Catalog of Somatic Mutations in Cancer, such as PlOD2, KEAP1, and PIH1D1." (PMID 39498880, 2025). "PLOD2 is a pro-metastatic oncoprotein strongly implicated in mediating the hypoxia response in cancer metastasis." (PMID 40775208, 2025). "Plod2 has been strongly implicated to promote epithelial to mesenchymal transition in various human cancers and preclinical models." (PMID 40482194, 2025). "In an effort to decipher the mechanism underlying PLOD2-driven cancer metastasis in ccRCC, we found that PLOD2 was also essential for selective activation of DCLK1-L." (PMID 40775208, 2025). "PLOD2 is a membrane-bound hydroxylase involved in extracellular matrix crosslinking that has been implicated in cancer cell migration as well as glycolysis." (PMID 36826702, 2023). "Exploratory studies on a small cohort of 28 GBM patients indicated that PLOD2 was also associated with poor survival in this type of cancer." (PMID 35682709, 2022). "PLOD2 encodes a key enzyme mediating the formation of the stabilized collagen cross-links, which are considered as the “highway” for cancer cell migration and invasion." (PMID 35300417, 2022). "PLOD2 encodes the key enzyme mediating the formation of the stabilized collagen cross-link, which sometimes can be considered as the “highway” for cancer cell migration and invasion." (PMID 35154316, 2022). "PLOD2 was dysregulated in various malignant tumors and always associated with poor prognosis, but the role of PLOD2 in CESC has rarely been demonstrated." (PMID 34258263, 2021). "Over the past several years, PLOD2 has been implicated as a protumorigenic agent in multiple cancers, particularly in cancer metastasis." (PMID 31170987, 2019). "Over the past several years, PLOD2 has been implicated as a protumorigenic agent in multiple cancers, with a specifically pivotal role in cancer metastasis." (PMID 30563531, 2018). "Over-deposition of collagen is the main cause of fibrosis, and aberrant PLOD2 expression contributes to the progression of collagen-related diseases such as fibrosis and cancer." (PMID 30563531, 2018). "By affecting collagen cross-links surrounding tumors, PLOD2 is associated with cancer progression." (PMID 36632453, 2023). "PLOD2 levels are significantly associated with advanced cancer staging." (PMID 36713509, 2022). "Although PLOD2 expression is reportedly associated with poor prognosis in several types of cancer 14-17, its role in chemoresistance remains unknown." (PMID 32284742, 2020). "Furthermore, the α-ketoglutarate-dependent enzyme PLOD2 can hydroxylate pro-collagen within the ER and has been implicated in hypoxic cancer cell invasion in various experimental models." (PMID 33050615, 2020). "Thus, we propose that loss of Rb or breakdown of this pathway primes cancer cells for metastatic transformation by allowing for the over-expression of pro-metastatic factors such as PLOD2 and CXCR4." (PMID 24919196, 2014). "Here we tested whether the fibrosis- and cancer-associated PLOD2 gene can be repressed by the DNA methyltransferase M.SssI, or by the non-catalytic Krüppel associated box (KRAB) repressor directed to the PLOD2 promoter via zinc finger- or CRISPR-dCas9-mediated targeting." (PMID 32455614, 2020). "The PLOD2 gene has been found to be upregulated in cancer, particularly in response to hypoxia and TGF-β1, and is associated with cancer progression and metastasis." (PMID 40906383, 2025). "Detailed isoform-specific functional investigations demonstrated that both DCLK1-L variants trigger cancer stemness and EMT activation and mediate hypoxia-PLOD2-induced malignant properties in ccRCC." (PMID 40775208, 2025).
cancer (continued). "In particular, PLOD2 is reported to stimulate the cancer stem cell phenotype and cisplatin resistance in cancer." (PMID 38316848, 2024). "PLOD2 + SAA1 + cancer cells with intricate crosstalk patterns indeed show promise for potential therapeutic interventions." (PMID 38951896, 2024). "PLOD2 has been identified with an oncogenic role and acts as a prognostic biomarker in several types of cancers." (PMID 38233403, 2024). "PLOD2 is a major enzyme in the modification of fibrotic collagen and its dysregulation enhances cancer progression metastasis." (PMID 36632453, 2023). "Patients with cancer with high PLOD2 expression (top) were significantly less likely to survive than those with cancer with low PLOD2 expression." (PMID 38008826, 2023). "HIF-1α induces the expression of P4HA1, P4HA2, PLOD1, and PLOD2 in different cancer and non-cancer cell lines, and enhanced activities of these enzymes are associated with increased collagen deposition in cancer tissue." (PMID 37490147, 2023). "It has also been displayed that procollagen-lysine, 2-oxoglutarate, PLOD2 promotes migration and invasion of cancer cells during hypoxia." (PMID 36624663, 2023). "The present study aimed to demonstrate a comprehensive workflow for pan-cancer analysis and to extensively investigate the role of PLOD2 as it related to various cancers." (PMID 35586565, 2022). "PLOD2 is a potential therapeutic target that increases cancer cell resistance and inhibits drug-induced apoptosis." (PMID 35330401, 2022). "Procollagen-lysine, 2-oxoglutarate 5-dioxygenase 2 (PLOD2) is a key gene in mediating the formation of the stabilized collagen cross-link, playing an important role in the progression of cancer." (PMID 36276118, 2022). "PLOD2 is a promising biomarker and a target for cancer therapy, but its exact role in GBM still requires characterization." (PMID 35682709, 2022). "PLOD2 was later found to be involved in immune infiltration in different cancer cell types(F. 11; Q. 12; B. 10)." (PMID 36276118, 2022). "Studies regarding the function of PLOD family enzymes in desmoplastic cancers have predominantly focused on the role of PLOD2." (PMID 35804902, 2022). "All these results demonstrated that PLOD2 was highly expressed in different types of cancer and participated in cancer progression and metastasis." (PMID 36276118, 2022). "PLOD2 is mainly located in the rough endoplasmic reticulum, shows wide tissue distribution, and has been demonstrated to enhance cancer cell motility and metastasis via the PI3K-AKT or TGF-β/Smad2 signaling pathways." (PMID 33495412, 2021). "Since PLOD2 has been reported to be positively regulated by PI3K-AKT signaling pathway activation in cancer cells, we used western blotting to evaluate P-AKT and P-Smad3 expression in PC12 cells." (PMID 33495412, 2021). "We found that the expression level of PLOD2 was increased in various cancers, and meta-analysis in the Oncomine database revealed that PLOD2 was significantly upregulated in CESC compared to that in normal tissues (P < 0.001)." (PMID 34258263, 2021). "PLOD2 can act as a direct regulator of cancer invasion/metastasis through specific interactions with integrin β1, a member of the integrin family of adhesion receptors." (PMID 34421605, 2021). "In many of these cancers, clinical data have shown that the increased expression of PLOD2 is an effective and independent factor of poor prognosis and is associated with decreased survival." (PMID 33805564, 2021). "Elevated expression of P4Hs and PLOD2 correlate with increased cancer cell adhesion to ECM and increased migration." (PMID 34202979, 2021). "The PLOD2-mediated changes in collagen organization are believed to play a key role in the migration and invasion of a wide variety of cancer cells." (PMID 33805564, 2021). "PLOD2 expression was up-regulated in various malignant tumors and negatively correlated with prognosis." (PMID 34179084, 2021).
cancer (continued). "In a variety of tumors, fibrous collagen is considered to provide a channel for cancer cell migration and is mainly modified by PLOD2." (PMID 35265665, 2021). "Knockdown of PLOD2 in pancreatic stellate cells limits the parallel-patterned fiber architecture formation and suppresses cancer cell directional migration in pancreatic cancer." (PMID 34202979, 2021). "We compared transcriptional levels of FKBP10, PLOD2 and pro-collagen I chains in cancer tissues with normal samples by inquiring ONCOMINE database." (PMID 34388114, 2021). "Promising new splice variants with a potential link with cancer are CSF1, PLOD2, SLK, SPAG9 and TSC2." (PMID 33845831, 2021). "Other secreted-proteins, such as MPS-1, ICAM-1, and PLOD2, have also been validated as critical downstream effectors of leptin in cancers." (PMID 33371368, 2020). "Attenuating PLOD2 expression has previously been shown to be a promising treatment against fibrosis and cancer metastasis in preclinical settings." (PMID 32455614, 2020). "As a result, we ascertained that CD44, PLOD1 and PLOD2 played a pro-cancer role in RCC through vitro experiments, reiterating that glycolytic risk signature was closely associated with RCC progression." (PMID 33287763, 2020). "Despite the efficient DNA methylation induced by M.SssI, PLOD2 repression was less pronounced (50% in fibroblasts; 75% in cancer cells) than SKD-induced repression (99% in both fibroblasts and cancer cell)." (PMID 32455614, 2020). "PLOD1 and PLOD2 are the key enzymes of collagen synthesis and extracellular matrix formation, therefore can drive tumorigenesis and angiogenesis in many cancers." (PMID 33287763, 2020). "Recently, fundamental evidence suggests that PLOD2 plays critical roles in the progression of cancer." (PMID 31455288, 2019). "PLOD2 reinforces the migration capacity of cancer cells, and also promotes cancer cells migration along the “highway” linear collagen." (PMID 31170987, 2019). "We found that PLOD2 was highly expressed in head and neck squamous carcinoma in the publicly available human cancer datasets of The Cancer Genome Atlas (TCGA)." (PMID 31455288, 2019). "Previous studies have demonstrated that PLOD2 expression is upregulated by both STAT3 and paracrine signals from cancer-associated fibroblasts (CAFs)." (PMID 30563531, 2018). "Minoxidil (a PLOD2 inhibitor) suppresses the expression of the PLOD2 protein, and significantly reduces cancer cell migration, resulting in an anti-metastatic effect both in vitro and in vivo." (PMID 29165393, 2017). "In multiple types of tumors, fibrotic collagen is regarded as the 'highway' for cancer cell migration, which is mainly modified by lysyl hydroxylase 2 (PLOD2)." (PMID 29072684, 2017). "Phase I and II trials are currently being pursued for CAIX, EGFRvIII, PLOD2, and EphA2 targeting chemotherapeutics in different types of cancer." (PMID 29165393, 2017). "Given that both hypoxia and PLOD2 play critical roles in α-promoter-preferred DCLK1 activation, and that PLOD2 is a known a hypoxia-responsive gene in multiple cancers, we hypothesized that PLOD2 mediates hypoxia-induced activation of DCLK1-L." (PMID 40775208, 2025). "In addition, Leptin has been shown to upregulate the expression of IL-8 in M2 macrophages and IL-18 in TAMs, increase the expression of PLOD2, and promote the metastasis of cancer cells." (PMID 39192979, 2024). "PLOD2 has oncogenic roles and acts as a prognostic biomarker in several types of cancers." (PMID 38233403, 2024). "On the other hand, PLOD2 may contribute to cancer progression by modulating aberrant collagen cross-link and maturation." (PMID 38233403, 2024). "Recently, there is growing evidence that PLOD2 plays a critical role in various cancers." (PMID 38008826, 2023). "IL-6 may promote cancer cell migration and invasion by enhancing the PLOD2-integrin β1 signaling pathway in OSCC cells." (PMID 36614179, 2023).
cancer (continued). "Thus, these promising studies in both epithelial and mesenchymal desmoplastic cancers indicate that the therapeutic potential of PLOD2 warrants further investigation in these contexts." (PMID 35804902, 2022). "First, we integrated GTEx, The Cancer Genome Atlas and Cancer Cell Line Encyclopedia databases to analyze the expression of PLOD2, and found that it was expressed differently in normal tissues and significantly highly expressed in most tumors compared with normal tissues." (PMID 35586565, 2022). "Collectively, PLOD2 played a significant role in tumorigenesis and maybe serve as a potential biomarker for diagnosis and prognosis in cancers." (PMID 35586565, 2022). "Pan-cancer analysis showed that PLOD2 was highly expressed in different cancer types." (PMID 36276118, 2022). "Previous studies on a small (n = 28) cohort of GBM patients suggested that PLOD2 may serve as a biomarker in this type of cancer." (PMID 35682709, 2022). "In addition, a close relationship was observed between PLOD2 expression and mutations in 4 methyltransferases (DNMT1, DNMT2, DNMT3A, DNMT3B) in several cancer types." (PMID 35586565, 2022). "Compared with normal tissues, PLOD2 was significantly upregulated in 11 cancer types." (PMID 35265665, 2021). "Obviously, PLOD2 is an independent factor of poor outcomes and could serve as a prognostic biomarker for patients with these cancer types." (PMID 35141213, 2021). "Moreover, its hub genes (CD44, PLOD1 and PLOD2) were proven to possess pro-cancer abilities through MTT and Transwell invasion assays." (PMID 33287763, 2020). "Among the GC patients, the PLOD2 high group had large amounts of collagen in their cancer tissues." (PMID 32284742, 2020). "Six of these validated genes (BIRC5, MK167, MMP9, PLOD2, and TOP2A) have previously been implicated ccRCC,21, 22, 23, 24, 25, 26, 27, 28, 29, 30, 31, 32, 33, 34 while the others have been implicated in other cancers." (PMID 32986937, 2020). "Definitely, the abnormal expression of PLOD2 may contribute to the development and progression of several types of cancer." (PMID 32258155, 2020). "Procollagen-lysine, 2-oxoglutarate 5-dioxygenase 2 (PLOD2) is thought to be a novel prognostic factor in several cancers, but its role in LSCC remains unknown." (PMID 31455288, 2019). "Moreover, the E2Fs36 and FOXA137 transcription factors have been demonstrated as regulators of PLOD2 during cancer progression." (PMID 30770789, 2019). "In addition, the elevated PLOD2 expression in stromal cells promoted the alteration of collagen structure deposited by the stromal cells, which further enhanced cancer cells migration along the linearity collagen." (PMID 31170987, 2019). "Furthermore, the conditioned medium of cancer cells (MDA-231-CM or SKBR3-CM) significantly stimulated the PLOD2 expression in adipocytes, while the PAI-1 inhibitor reversed the promotion effect." (PMID 31170987, 2019). "The function and mechanism of PLOD2 in several types of cancer have been explored." (PMID 31455288, 2019). "Recent studies have shown that PLOD2 is closely related to cancer metastasis." (PMID 30563531, 2018). "In addition, transcription factor E2Fs and FOXA1 have been identified as regulators of PLOD2 during cancer progression." (PMID 30003082, 2018). "Knockdown of PLOD2 significantly inhibits cancer cell migration and invasion." (PMID 30563531, 2018). "The overexpression of PLOD2 is detected in many types of cancer." (PMID 30003082, 2018). "Even though there have been substantial advances in targeting PLOD2 in different types of cancer, to date, the effectiveness of these anti-PLOD2 agents in GBM models remains unknown." (PMID 29165393, 2017). "In addition, the expression of PLOD2 was related to the prognosis of cancer patients (6–9; B. 10)." (PMID 36276118, 2022). "Thus, PLOD2 has been regarded as a novel prognostic factor in many types of cancer." (PMID 32258155, 2020).